GPR132 (G protein-coupled receptor 132)
Description:
May be a receptor for oxidized free fatty acids derived from linoleic and arachidonic acids such as 9-hydroxyoctadecadienoic acid (9-HODE). Activates a G alpha protein, most likely G alpha(q). May be involved in apoptosis. Functions at the G2/M checkpoint to delay mitosis. May function as a sensor that monitors the oxidative states and mediates appropriate cellular responses such as secretion of paracrine signals and attenuation of proliferation. May mediate ths accumulation of intracellular inositol phosphates at acidic pH through proton-sensing activity.
Synonyms: G2A
Tractability: Small molecule: a structure with a bound ligand is known; it belongs to a druggable protein family. Antibody: UniProt places it where antibodies can reach, with high confidence; its Gene Ontology location is reachable by antibodies, with high confidence; UniProt predicts a signal peptide or a membrane-spanning region.
Target class: Family A G protein-coupled receptor; Membrane receptor
Chemical probes: T-10418 (high quality)
Gene: Protein-coding gene on chromosome 14 (105,048,658 to 105,065,940, reverse strand). Ensembl gene ENSG00000183484.
Subcellular location: Cell membrane
Pathways (Reactome):
Signal Transduction: Class A/1 (Rhodopsin-like receptors); G alpha (q) signalling events
Gene Ontology:
Molecular function: G protein-coupled receptor activity
Biological process: G1/S transition of mitotic cell cycle; negative regulation of G2/M transition of mitotic cell cycle; G protein-coupled receptor signaling pathway
Cellular component: plasma membrane; membrane
Genetic constraint (gnomAD): Loss-of-function variants: 2 observed, 1.66 expected, observed/expected ratio (o/e) 1.2, 90% interval 0.41 to 1.9. That is too few expected variants to judge how well the gene tolerates losing a copy. Missense variants: 394 observed, 524.52 expected, observed/expected ratio (o/e) 0.75, 90% interval 0.69 to 0.82. Synonymous variants: 229 observed, 240.08 expected, observed/expected ratio (o/e) 0.95, 90% interval 0.86 to 1.06.
Homologues: Orthologues: guinea pig GPR132 (66% identical), rat Gpr132 (66% identical). Paralogues in human: RXFP3 (21% identical), GPR183 (20% identical), GPR174 (19% identical), P2RY11 (17% identical), GPR141 (14% identical), GPR151 (12% identical), GPR146 (8% identical).
Diseases named in the same sentence as GPR132 in open-access papers:
GPR132 is named in the same sentence as 39 diseases in open-access papers, as found by Europe PMC text mining. Sharing a sentence is not in itself a finding about the gene and the disease. The quoted sentences say what the papers report.
breast carcinoma (30 papers, 2016 to 2025). "G-protein-coupled receptor 132 (Gpr132) on macrophages mediates the sensation of lactate by M2 polarized macrophages, and the metastasis of breast cancer is suppressed with the loss of Gpr132 in mice." (PMID 33413697, 2021). "Because GPR132 is reported to be sensitive to lactate in the breast cancer microenvironment, we treated GPR132-deficient NK92 cells and normal NK92 cells with lactate, and the results demonstrated that the GPR132 knockdown can lessen lactate-induced inhibition of NK92 cells." (PMID 40043109, 2025). "Correspondingly, lactate can promote the M2-like phenotype by activating G-protein-coupled receptor 132 (GPR132) in macrophages, and genetic deletion of Gpr132 in macrophages reduces the M2-like features of tumor-associated macrophages and decreases lung metastasis in a mouse breast cancer model." (PMID 38650924, 2024). "A recent study found that rosiglitazone may inhibit breast cancer growth in mice by suppressing the expression of a pro-inflammatory and pro-tumor protein Gpr132 in tumor-associated macrophages." (PMID 27936468, 2017). "Lower Gpr132 expression is associated with better survival in breast cancer patients, so targeting the lactate-Gpr132 axis may help to abrogate the M2 phenotypic polarization of TAMs and lung metastasis of breast cancer." (PMID 37564659, 2023). "And it has been shown that the enhanced expression of Gpr132 relates to the worse outcome of breast cancer patients, which was further verified by the positive association between the Gpr132 level and M2 macrophages infiltration, metastasis, and poor prognosis in breast cancer models in mice." (PMID 31300030, 2019). "An in vivo study demonstrated that tumor-derived lactate activated macrophage G protein-coupled receptor 132 (GPR132), promoting the tumor associated macrophage (TAM) phenotype in breast cancer." (PMID 41373022, 2025). "A previous study suggested that the lactate–Gpr132 axis is a driver of breast cancer metastasis by stimulating tumor–macrophage interplay and revealed potential new therapeutic targets for breast cancer treatment." (PMID 40761790, 2025). "In the breast cancer microenvironment, GPR132 inhibitors interfere with the lactate-GPR132-peroxisome proliferator–activated receptor γ axis and encourage tumor-associated macrophages to the M1-phenotype transformation." (PMID 40043109, 2025). "Extensive research has underscored the significance of the lactate-GPR132 axis in driving the metastatic potential of breast cancer, primarily by facilitating tumor-macrophage interactions." (PMID 39867891, 2024). "The interaction of GPR132 with lactate fosters breast cancer metastasis and ameliorates insulin resistance by inducing macrophage phenotypic shifts." (PMID 39867891, 2024). "Upon sensing lactate abundance in the TME, macrophage G-protein coupled receptor 132 (Gpr132) polarizes into M2-like macrophages, a process that promotes metastasis and invasion in breast cancer." (PMID 38185636, 2024). "In breast cancer, Gpr132 on BMDMs was reported to sense lactate and mediate TAMs interplay, promoting tumor metastasis." (PMID 38576043, 2024). "Lactate activates Gpr132 to promote alternatively activated macrophage (M2)-like phenotype, uncovering the lactate-Gpr132 axis as a driver of breast cancer metastasis by stimulating tumor-macrophage interaction." (PMID 37426676, 2023). "The clinical context between GPR132 expression, M2 macrophages, metastasis, and a poor prognosis in patients with breast cancer is clear." (PMID 36902589, 2023). "In breast cancer, lactate activates macrophage Gpr132 to transform into the M2-like phenotype, uncovering the lactate-Gpr132 axis as a driver of breast cancer metastasis by stimulating tumor-macrophage interplay." (PMID 37507768, 2023).
breast carcinoma (continued). "In a co-culture study of breast cancer cells and macrophages, G protein-coupled receptor 132 (Gpr132) senses lactate in the tumor environment to transform macrophages into M2-like phenotypes to promote cancer cell adherence, migration, and invasion." (PMID 34552932, 2021). "Another critical study has demonstrated that blocking GPR132 signaling in macrophages markedly reduced tumor burden, progression, and breast cancer metastasis in mice." (PMID 34394085, 2021). "Concordantly, high GPR132 expression in breast cancer tumors correlated with the expression of M2 macrophage markers and low metastasis-free and relapse-free survival." (PMID 33324565, 2020). "Clinical data show a positive correlation in breast cancer between GPR132, M2 macrophages, metastasis and poor patient prognosis, while GPR132 deletion in a mouse model of breast cancer inhibits metastasis to the lung." (PMID 36046070, 2020). "Recently, GPR132 has been shown to be involved as a macrophage lactate sensor in the acidic TME during metastasis of breast cancer." (PMID 36046070, 2020). "G protein-coupled receptor 132 (Gpr132) mediates the interplay between TAMs and breast cancer cells via sensing altered lactate to promote metastasis." (PMID 32296646, 2020). "Gpr132 expression positively correlated with M2 macrophages, metastasis, and poor prognosis in patients with breast cancer." (PMID 30597969, 2018). "To explore the significance of Gpr132 in human breast cancer, we analyzed the RNA-Seq and clinical data of breast invasive carcinoma (BRCA) from The Cancer Genome Atlas (TCGA) database." (PMID 27692066, 2016). "This genetic rescue further supports that Gpr132 is an essential mediator of macrophage PPARγ regulation of breast cancer progression." (PMID 27692066, 2016). "Immunohistochemistry staining confirmed that human breast cancer tissues expressed significantly higher Gpr132 compared with normal breast control tissues." (PMID 27692066, 2016). "The inhibition of Gpr132 has been shown to reduce the metastasis of breast cancer." (PMID 38185636, 2024). "lactate has been shown to bind to macrophage GPR132, thereby promoting the polarization of macrophages towards the M2 phenotype, which in turn enhances the adhesion, migration, and invasive capabilities of breast cancer cells." (PMID 39867891, 2024). "GPR132 is linked to M2 macrophages and metastasis in human breast cancer, but GPR132-KO mice do not experience metastasis." (PMID 38668345, 2024). "Consequently, GPR132 deletion reduces M2 macrophages and impedes breast cancer lung metastasis in mice." (PMID 34394085, 2021). "Furthermore, the decrease of Gpr132 expression is related to the improvement of metastasis-free survival in breast cancer patients." (PMID 33413697, 2021). "Moreover, abrogating the lactate/GPR132 axis impedes M2 polarization and breast cancer metastasis in mice." (PMID 33324565, 2020). "Compared with normal breast samples, the majority of breast cancer lesions displayed significantly higher Gpr132 expression; in addition, compared with ER-positive breast cancers, the more aggressive ER-negative breast cancers also exhibited higher Gpr132 expression." (PMID 27692066, 2016). "To further explore Gpr132 as a potential cancer therapeutic target, we next examined whether acute pharmacological inhibition of Gpr132 could attenuate breast cancer progression." (PMID 27692066, 2016). "Pharmacological Gpr132 inhibition significantly impedes mammary tumor malignancy." (PMID 27692066, 2016). "Considering that G protein-coupled receptor 132 (Gpr132) has been identified as a key macrophage sensor of lactate that mediates the interaction between breast cancer cells and TAMs, activation of the PKA/CREB signaling pathway might be involved in lactate-mediated M2-like TAM polarization." (PMID 35246504, 2022).
breast carcinoma (continued). "On the other hand, lactate activated macrophage G protein-coupled receptor 132 (Gpr132) to promote an alternatively activated macrophage (M2)-like phenotype, which in turn facilitated cancer cell migration and invasion to promote lung metastasis in breast cancer." (PMID 33178603, 2020). "GPR132 expression appears to be suppressed by PPARg activators such as the thiazolidinediones, which may suggest these as possible anti-metastic treatments in breast cancer." (PMID 36046070, 2020). "Moreover, Gpr132 deletion reduced M2 macrophages in lungs and impaired breast cancer metastasis." (PMID 30597969, 2018). "Because the effect of pioglitazone on Gpr132 expression has not been examined, it remains unknown whether different drugs in the class of thiazolidinediones may exert different effects on breast cancer risk through their discrepant effects on Gpr132." (PMID 27936468, 2017). "A nomogram was constructed using 7 IRGs, including GPR132, IFITM1, IL12B, IL18, IRF7, KCNMB2, and TACR1, to predict the 1-, 2-, and 3-year survival of breast cancer patients." (PMID 37304237, 2023). "G protein-coupled receptor 132 (GPR132) expressed on macrophages senses lactate within TME and leads macrophages to adopt M2-like phenotypes to promote breast cancer metastasis." (PMID 36244976, 2022). "To examine the effects of Gpr132 deletion in the tumor environment on cancer growth in vivo, we injected EO771 mouse breast cancer cells into the mammary fat pad of Gpr132-KO mice and WT littermate controls." (PMID 27692066, 2016). "Moreover, it can activate G-protein-coupled receptor 132 (GPR132), inducing the differentiation of TAMs into the M2 subtype and facilitating breast cancer metastasis." (PMID 38672455, 2024). "Because Gpr132 is highly expressed in human macrophages but absent in human breast cancer cells, the Gpr132 expression in tumors mainly originates from hematopoietic cells in the microenvironment such as macrophages." (PMID 27692066, 2016). "Moreover, linear regression analyses showed that higher Gpr132 expression was significantly correlated with higher expression of pro-inflammatory markers including CCL2 (MCP-1), MMP9 and PTGS2 (COX-2) in breast cancer lesions." (PMID 27692066, 2016). "Interestingly, expression of GPR132 is almost non-existent in breast cancer cells, suggesting that anti-metastatic effects occur via stromal elements in the tumour." (PMID 36046070, 2020).
atherosclerosis (8 papers, 2020 to 2025). A disease characterized by the build-up of fatty material and calcium deposition in the arterial wall resulting in partial or complete occlusion of the arterial lumen. "Commendamide resembles long-chain N-acyl-amino acids that function as mammalian signaling molecules through activation of GPCRs or PPARs, such as N-oleoyl-glycine, and was found to activate GPCR G2A/GPR132, which has been implicated in autoimmunity and atherosclerosis." (PMID 32106469, 2020). "Then, Gpr132−/−Apoe−/− mice were generated to investigate the role of GPR132 in atherosclerosis in vivo." (PMID 40492515, 2025). "The deletion of Gpr132 has been shown to ameliorate atherosclerosis, while the inhibition of the Src pathway using saracatinib presents a promising therapeutic strategy for addressing diabetic atherosclerosis." (PMID 40492515, 2025). "Inhibiting the GPR132-Src pathway alleviated atherosclerosis, providing a treatment strategy for diabetic cardiovascular complications independent of lipid-lowering." (PMID 41403700, 2025). "Elevated glucose levels stimulate lactate‐mediated paracrine signaling that activates GPR132‐Src pathways; the deletion of GPR132 or inhibition of Src was found to alleviate atherosclerosis." (PMID 40492515, 2025). "Studies conducted on atherosclerosis-prone animal models have shown that GPR132 has a role in controlling atherosclerosis." (PMID 39599599, 2024). "Further, 9 HODE is the most potent ligand involved in the pathogenesis of atherosclerosis, via GPR132; but on the other hand, 13 HODE affects the adhesion of platelets to the endothelial wall." (PMID 36672599, 2022). "Another lactate receptor, GPR132, plays a significant role in the context of atherosclerosis." (PMID 41403700, 2025). "Importantly, there was a notable decrease in p21+ macrophages within the aortic roots and a reduction in β‐gal staining in the aorta, suggesting that GPR132 functions as a promoter of cellular senescence in the context of atherosclerosis." (PMID 40492515, 2025). "The deletion of GPR132 markedly reduces macrophage senescence and atherosclerosis in mouse models." (PMID 40492515, 2025). "In 2015, it was reported that lipid metabolite commendamide (N-acyl 3-hydroxy-palmitoyl glycine) is an agonist of the host G-protein coupled receptor (GPCR) GPR132/G2A, which plays key roles in monocyte chemotaxis and macrophage function contributing to atherosclerosis." (PMID 41209147, 2025). "Unlike GPR132, 13-HODE does not act as a ligand and primarily has protective properties against inflammation and atherosclerosis." (PMID 39599599, 2024).
ovarian carcinoma (7 papers, 2018 to 2025). A malignant neoplasm originating from the surface ovarian epithelium. "The family includes T-cell death-associated gene 8 (TDAG8 or GPR65), ovarian cancer G-protein coupled receptor 1 (OGR1 or GPR68), G2 accumulating protein (G2A or GPR132), and GPR4." (PMID 36233248, 2022). "It belongs to a small G protein-coupled proton-sensing receptor family that includes ovarian cancer G protein-coupled receptor 1 (OGR1), also referred to as GPR68, G2A, also termed GPR132, and T-cell death-associated gene 8 (TDAG8), also known as GPR65." (PMID 33053856, 2020). "This subfamily of proteins is composed of four members: G protein-coupled receptor 4 (GPR4 or Gpr4), T-cell death–associated gene 8 (TDAG8 or Gpr65), ovarian cancer G protein–coupled receptor 1 (OGR1 or Gpr68), and G protein–coupled receptor 132 (G2A or Gpr132)." (PMID 35247105, 2022). "The family of GPCR includes the ovarian cancer G protein-coupled receptor 1 (OGR1, also known as GPR68), the G protein-coupled receptor 4 (GPR4), the T cell death-associated G protein 8 (TDAG8, also known as GPR65), and the G2 accumulation protein (G2A, also known as GPR132)." (PMID 30825056, 2019). "Recent studies have identified lactate as a ligand for GPR68, GPR81, and GPR132, also known as ovarian cancer G protein-coupled receptor 1 (OGR1), hydroxy-carboxylic acid receptor 1 (HCAR1) and G2 accumulation protein (G2A), respectively." (PMID 40046050, 2025).
acute myeloid leukemia (4 papers, 2021 to 2025). Acute myeloid leukemia (AML) is a group of neoplasms arising from precursor cells committed to the myeloid cell-line differentiation. "Nonetheless, GPR132 agonist activation of a GPR132-Gs-PKA pathway interfered with mTOR signaling and promoted acute myeloid leukemia (AML) cell differentiation, suggesting a therapeutic approach to AML treatment." (PMID 40333742, 2025). "In this study, we identified SE-associated genes by integrating cell-specific SEs with RNA-seq data and found six genes (CAPG, CD207, GPR132, SLC7A11, HIPK3 and FCER1G) that are correlated with poor prognosis in acute myeloid leukemia (AML) patients according to the TCGA-LAML database." (PMID 37296281, 2023).
breast tumor (4 papers, 2019 to 2024). "GPR132 expression is reduced by the activation of peroxisome proliferator-activated receptor γ (PPARγ) in tumor-associated macrophages (TAMs); moreover, breast tumor cells produce lactate which activates GPR132 in TAMs, promoting macrophage M2 activation and tumor growth." (PMID 35095895, 2021). "Increased levels of GPR132 promote the infiltration of protumoral MDMs into breast tumors, while the pharmacological inhibition and genetic deletion of GPR132 reduce tumor growth and metastasis." (PMID 38411356, 2024). "PPARγ agonists, which are suppressive for the Gpr132 axis, or siRNA silencing of Gpr132, was successfully used to desensitize TAMs to lactate stimulation in a breast tumor model." (PMID 31547627, 2019).
colitis (4 papers, 2020 to 2025). Inflammation of the colon. "In a striking functional similarity with GPR81 knockout mice, genetic deficiency of GPR132 also resulted in significantly worsened chemically-induced colitis in mice." (PMID 34394085, 2021). "GPR132-mediated signaling in myeloid and lymphoid cells limits intestinal inflammation in a mouse model of colitis induced by dextran sodium sulfate." (PMID 34394085, 2021).
diabetes (3 papers, 2016 to 2025). "Elevated lactate in diabetes activates the GPR132‐Src pathway in macrophages, inducing macrophage senescence and further enhancing foam cell formation." (PMID 40492515, 2025). "Ultimately, these new knowledge will enhance our understanding of macrophage regulation, cancer microenvironment as well as PPARγ and Gpr132 biology, which may translate to a better intervention of diseases such as cancer, diabetes and inflammatory disorders." (PMID 27692066, 2016).